TMEM254 (transmembrane protein 254)
Synonyms: C10orf57; FLJ13263; bA369J21.6
Tractability: Antibody: UniProt predicts a signal peptide or a membrane-spanning region; the Human Protein Atlas places it where antibodies can reach.
Gene: Protein-coding gene on chromosome 10 (80,078,646 to 80,092,557, forward strand). Ensembl gene ENSG00000133678.
Subcellular location: Membrane
Subcellular location (Human Protein Atlas): Plasma membrane; Nucleoplasm
Gene Ontology:
Molecular function: protein binding
Cellular component: membrane
Genetic constraint (gnomAD): Loss-of-function variants: 23 observed, 19.09 expected, observed/expected ratio (o/e) 1.21, 90% interval 0.87 to 1.69. The upper end of that interval is the gene's LOEUF score, 1.69, which puts it in group 6 of 6, group 1 being the genes least tolerant of losing a copy. Missense variants: 155 observed, 147.23 expected, observed/expected ratio (o/e) 1.05, 90% interval 0.92 to 1.2. Synonymous variants: 61 observed, 55.29 expected, observed/expected ratio (o/e) 1.1, 90% interval 0.9 to 1.37.
Homologues: Orthologues: chimpanzee TMEM254 (100% identical), macaque TMEM254 (92% identical), dog TMEM254 (84% identical), mouse Tmem254 (81% identical), guinea pig TMEM254 (65% identical), rat Tmem254 (64% identical), pig TMEM254 (63% identical), tropical clawed frog tmem254 (51% identical), zebrafish tmem254 (44% identical).
Diseases named in the same sentence as TMEM254 in open-access papers:
TMEM254 is named in the same sentence as 1 disease in open-access papers, as found by Europe PMC text mining. Sharing a sentence is not in itself a finding about the gene and the disease. The quoted sentences say what the papers report.
tumor (1 paper, 2023). "The molecules that were differentially expressed in tumor and normal tissues by R software analysis were TMEM79, SMG5, NAA35, SLC45A3, FLG, TMEM254." (PMID 37936239, 2023).